ERBB2 (erb-b2 receptor tyrosine kinase 2)
Diseases named in the same sentence as ERBB2 in open-access papers (continued):
Sharing a sentence is not in itself a finding about the gene and the disease.
breast cancer (continued). "Subsequently, we performed univariate and multivariate Cox regression analyses on the relationships among KNSTRN, HER2 (ERBB2), ER (ESR1), and Ki67 (MKI67) expression, clinical factors (age, race, and pTNM-stage), and OS in patients with breast cancer." (PMID 38198023, 2024). "Trastuzumab is a monoclonal antibody that targets erbB-2 and erbB-3 receptorsand is used to treat HER2-positive breast cancer." (PMID 39076943, 2024). "We focused on 23 pathways with greater than 20% gene overlap with ERBB2, illustrating their potential relevance to HER2-positive breast cancer." (PMID 39684551, 2024). "NRAS (breast carcinoma and skin melanoma), CDK4 (NSCLC), and ERBB2 (gastric carcinoma and esophageal carcinoma) were identified as the top identified amplification driver genes in different cancer types." (PMID 38195844, 2024). "In colon and breast carcinoma cells, elevated levels of HA result in the formation of a signaling complex involving CD44 and ErbB2, along with PI3K, ezrin, HSP90, and CDC37." (PMID 37953485, 2024). "In breast cancer cells, a positive feedback loop involving HA, PI3K, and ErbB2 strongly amplifies the expression of MDR1 and increases resistance to doxorubicin." (PMID 37953485, 2024). "Similar to FGFR4/ERBB2, the overall correlation between GPR160 and TMEM45B expression in TCGA breast cancers appeared in the lower spectrum (Spearman rho = 0.35)." (PMID 37857634, 2023). "ERBB2 (also known as HER2) is a commonly amplified and overexpressed proto-oncogene in a subset of breast cancer." (PMID 37255594, 2023). "In this study, we demonstrated that Shc3 acts as a novel binding protein of EphA2 and ErbB2 linking that activated Akt and MAPK pathways to mediate drug resistance and aggressive behavior in breast cancer." (PMID 36880347, 2023). "The expression levels of ERBB2, CCND1, and BCL2 were significantly higher in the breast cancer component than in the FAs." (PMID 37328469, 2023). "In breast cancer, ERK5 contributes to the response to EGF stimulation and is involved in the resistance to ErbB-2 (HER2) inhibitors by facilitating G1-S transition." (PMID 37420093, 2023). "There are several subtypes of breast cancer, among which the HER2+ subtype is characterized by the increased expression of ERBB2 (also known as HER2) in tumor cells." (PMID 36857450, 2023). "Our previous study demonstrated that ERBB2 promotes autophagy by upregulating the essential autophagy pathway protein, ATG12 (autophagy-related 12), in breast cancer cells." (PMID 40395294, 2023). "PPRHs designed against two intronic sequences of the ERBB2 gene decreased the viability of SKBR-3 and MDA-MB-453 breast cancer cells." (PMID 37108234, 2023). "Human epidermal growth factor receptor 2 (HER2) protein, which is characterized by the amplification of ERBB2, is a molecular target for HER2-overexpressing breast cancer." (PMID 37759508, 2023). "Turcotte et al36 showed that, in HER2+ breast cancer, NT5E expressed by tumor cells and host cells significantly suppresses the anti‐ErbB2‐mediated immune response, thereby promoting resistance to targeted therapy." (PMID 37792675, 2023). "In breast cancer cells, HSF1 and ErbB2 (HER2) work together to promote glycolysis, cell migration, and invasion." (PMID 37958341, 2023). "AREG is involved in regulating the proliferation and migration of erbB2- and HER2-positive breast cancer cells." (PMID 37604948, 2023). "ERBB2 amplification and HER2 overexpression have been the most extensively studied in breast cancer." (PMID 37747019, 2023).
breast cancer (continued). "Case 6 is an adult patient with right-sided breast cancer with positive PD-L1 expression and disruption of the CD274 3' UTR region accompanied by driver gene ERBB2 amplification." (PMID 36717553, 2023). "In those cases, the expression of breast cancer markers, such as ESR1 and ERBB2, was relatively low in the HER2-2 and luminal-3, -6, and -11 cases." (PMID 37759508, 2023). "In our results, heterogeneous distribution of the expression of breast cancer-related genes (ESR1, PGR, ERBB2, and MKI67) was observed." (PMID 37759508, 2023). "Noteworthily, 15-20% of patients with breast cancer overexpress the human epidermal growth factor receptor (EGFR) 2, also known as HER2, ERBB2 or CD340." (PMID 37957717, 2023). "IHC scores of 1+ or 2+ breast cancer have been classified as HER2-low breast cancer, and ERBB2-targeted therapy (trastuzumab deruxetecan) showed prolonged survival in patients with HER2-low breast cancer." (PMID 37759508, 2023). "In addition, a significant and inverse association has also been observed between quantitative measurements of ERBB2 gene copy number and ER/progesterone receptor (PR) protein expression levels in breast cancer, which may further explain the relative resistance of HR+/HER2+ tumors to ETs8." (PMID 37258523, 2023). "It has been shown that HK2 is required for tumorigenesis in an ErbB2/ Her2‐driven breast cancer mouse model, and HK2 ablation inhibits the malignant phenotype of breast cancer cells in vitro and in vivo." (PMID 36807772, 2023). "FGFR4 was specifically selected as a gene overexpressed in HER2ENC7, but it displays a lesser correlation to ERBB2, a prototypical HER2ENC gene, in SCAN-B data but also TCGA breast cancers when analyzed through the cBioPortal online tool (Spearman rho = 0.24)." (PMID 37857634, 2023). "Collectively, our findings suggested that the interaction of Shc3 with EphA2 and ErbB2 plays an important role in MDR and aggressive behavior of breast cancer." (PMID 36880347, 2023). "As for CNAs, Ecotype 2 had the highest frequency of ERBB2 (17q12, 50.4%) amplification, which was in line with the high proportion of HER2+ breast cancers of this ecotype." (PMID 37880211, 2023). "Mass morphology breast cancer cell types include T-47D, MCF7, BT-474, HCC1569, and HCC70, all of which have the highest level of proton ErbB-2 expression from western blot analysis." (PMID 38137912, 2023). "We validated the functionality of the system with two different CAR-NK cell lines specific for PD-L1 and ErbB2 (PD-L1.CAR NK-92 and ErbB2.CAR NK-92 cells) against the PD-L1-expressing MDA-MB-231 and ErbB2-expressing MDA-MB-453 breast cancer cell lines." (PMID 37885894, 2023). "TNBC is the general term for breast cancers devoid of ER, PR, and HER2 (ERBB2) expression; however, it is characterized by substantial inter–patient heterogeneity." (PMID 36672419, 2023). "In breast cancer, CDK12 frequently displays co-amplification and cooperation with the ERBB2 and interaction with oncogenic pathways, such as IRS1-ErbB-PI3K signaling." (PMID 38049758, 2023). "Approximately 12 to 17% of breast cancer patients are diagnosed with triple-negative breast cancer (TNBC), a subtype that has low expression of HER-2/ERBB2 and lacks both estrogen and progesterone receptors." (PMID 37239157, 2023). "Based on the expression status of the estrogen receptor (ER-a), progesterone receptor (PR) and human epidermal growth factor 2 receptor (HER2/ERBB2), breast cancer is classified as luminal A, luminal B, HER2 positive and TNBC." (PMID 37365643, 2023). "Previous research showed that EphA2 and ErbB2 can form a complex, resulting in increased activation of the RhoA GTPase and MAPK pathways in breast cancer cells." (PMID 36880347, 2023). "Approximately 15% of breast cancers are classified as HER2-positive, with an amplification of the ERBB2 gene and/or an overexpression of the HER2 protein." (PMID 36900178, 2023).
breast cancer (continued). "For example, translocations between 11q and 17q were observed in 16 out of 25 breast cancers that have co-amplifications of CCND1 and ERBB2, with some cases showing a remarkably similar pattern of copy number and rearrangements." (PMID 37198482, 2023). "HER2+ breast cancer is characterised by amplification of the ERBB2 gene (chromosome assignment 17q12), leading to overexpression of the HER2 protein." (PMID 37507543, 2023). "The breast cancer-acquired amplification of ERBB2 has been targeted with anti-HER2 antibodies, biologics, and small-molecule ERBB2 kinase inhibitors." (PMID 36672285, 2023). "Note also that important genes distinguishing between cancer subtypes, e.g., for breast cancer, like ERBB2 (HER2), ESR1 (ER), and two forms of membrane component of PR, PGRMC1 and PGRMC2, survived shambhalization." (PMID 37745690, 2023). "Approximately 60 to 70% of breast cancers express the estrogen receptor (ER+), 10 to 15% are ERBB2-amplified (HER2+), and 10 to 15% are triple-negative breast cancers (TNBC) that are ER-, PR-, and Her2-." (PMID 36672285, 2023). "EGFR, ERBB2, and ERBB4 fusions were most frequently found in glioblastoma, breast cancer and ovarian cancer, respectively." (PMID 37168365, 2023). "Further investigation showed that genetic deletion of ILK in ErbB2-activated mammary tumours led to YAP inactivation, indicating an essential role for YAP activation in ErbB2-induced mammary tumourigenesis." (PMID 36759723, 2023). "A rapid increase and decrease of PYK2 activation in breast cancer cells has also been shown to increase PYK2 complex formation with p190 RhoGAP (p190), RasGAP, ErbB-2, and Src, leading to activation of the MAPK signalling and increase of cancer cell invasion." (PMID 37055381, 2023). "In murine ErbB2-induced and human HER2-enriched breast carcinomas, extracellular carbonic anhydrases increase immune cell infiltration and cytokine expression, decelerate tumor growth, and improve survival." (PMID 37098526, 2023). "Among all the cancers related to ERBB2 amplification and HER2 over-expression, breast cancer is most widely studied." (PMID 36276102, 2022). "HER2, also known as erb-b2 receptor tyrosine kinase 2 (ERBB2), is a transmembrane tyrosine kinase receptor that is overexpressed in around 20% of all breast cancers, leading to a poor prognosis for patients." (PMID 36466034, 2022). "However, activated PKCα attenuates Jagged-1-mediated Notch1 activity in ErbB2-positive breast cancer and restores trastuzumab resistance, suggesting that PKCα activity may be a potential prognostic marker for low Notch activity and increased trastuzumab sensitivity in ErbB2-positive breast cancer." (PMID 36358843, 2022). "For instance, certain mutations in ErbB1 (EGFR) and the amplification/overexpression of ErbB2 provide important targets for interrogation in non-small cell lung cancer (NSCLC) and breast cancer, respectively." (PMID 36230550, 2022). "Several samples had missing or ambiguous status for the two main prognostic and treatment‐predictive biomarkers in breast cancer: oestrogen receptor alpha (ER, gene symbol ESR1) and Erb‐B2 receptor tyrosine kinase 2 (HER2, gene symbol ERBB2)." (PMID 35182081, 2022). "In breast cancer, inhibition of FAK expression with small-molecule inhibitors significantly increased the sensitivity of breast cancer cells to the ErbB2 antibody trastuzumab." (PMID 35965583, 2022). "Collectively, these data in HER2+ breast cancer cells demonstrate that NRG4 activates ERBB4 and boosts the anti-proliferative effects of anti-ERBB2 agents." (PMID 35664762, 2022). "Based on their distinctive molecular profiling, breast cancers can be grouped in different subtypes: estrogen-receptor positive luminal, ERBB2+ (or HER2+), basal-like (also referred as triple negative due to absence of ER, PR and HER2) and claudin-low." (PMID 36233192, 2022).
breast cancer (continued). "In breast cancers, ML364 potentiates the pro-degradation effects of HSP90 inhibitors on ErbB2 and hence sensitizes ErbB2-positive cells to HSP90 inhibition." (PMID 35307036, 2022). "Breast cancer is categorized into luminal A, luminal B, ERBB2/HER2, basal-like and triple-negative (TN) subtypes." (PMID 35768871, 2022). "Fifteen to twenty percent of patients with early breast cancer (EBC) will have over-expression of Human Epidermal Growth Factor Receptor-2 (HER2/ERBB2), an aggressive breast cancer subtype with a classically poorer prognosis." (PMID 35735438, 2022). "In a later publication using a tyrosine antibody array, several RTKs able to bind to PKM2 were detected, and their ability to phosphorylate PKM2 was confirmed when overexpressed in a breast cancer cell line (Axl, EpHA2, FAK, Tyro3, ErbB2, 29440169)." (PMID 35054968, 2022). "Breast cancer with high level of GDF15, especially in ErbB2 (HER2)-positive state, is sensitive to EGFR/ErbB2 inhibitor Lapatinib." (PMID 35853851, 2022). "The transmembrane receptor ERBB2 is a tyrosine kinase and belongs to the family of EGFR and plays a prominent role in breast cancer." (PMID 35937803, 2022). "The data showed strong activation of T-lymphocytes mediated by αCD3-αHER2 SMART-Exos in an ERBB2-positive cancer cell-dependent manner in vitro, and their cytotoxicity against HER2-expressing breast cancer was CD3+T cells-dependent." (PMID 35209095, 2022). "A notable example is the Erb-B Receptor Tyrosine Kinase family of ERBB genes; one of which, isoform ERBB2, also commonly referred to as HER2, has recently shown clinical relevance not only in breast cancer, but also in gynecological malignancies." (PMID 35740327, 2022). "Lapatinib is an orally administered, dual ErbB1 and ErbB2 TKI and proven effective in treating ErbB2-positive breast cancer." (PMID 35800225, 2022). "HER2low breast cancers showed a significant higher number of HER2 copies and a higher ERBB2 gene-expression compared to HER2- tumors, which is in line with previous studies." (PMID 35902644, 2022). "In fact, the lnc-RNA AFAP1-AS1 is present in CAF EVs and enhances the translation of ERBB2 mRNA by binding to AUF1, to induce the upregulation of HER-2 protein levels and subsequently trastuzumab resistance in breast cancer cells." (PMID 35646668, 2022). "Its main use is in blocking the growth of the human epidermal factor 2 receptor (ERBB2, HER2) and the epidermal growth factor receptor in the treatment of breast cancer." (PMID 35054822, 2022). "Detection of ERBB2 CNG by tissue NGS and ctDNA has a high PPV for true HER2-positivity by standard IHC and/or FISH testing in breast cancer." (PMID 35126865, 2022). "A clinical phase I/II assay evaluated a peptide-based vaccine that contained peptides derived from the TAA: MUC1 (SAPDNRPAL), CEA (YLSGADLNL), and ErbB2 (KIFGSLAFL) in patients with ovarian and breast cancer." (PMID 36016136, 2022). "Trastuzumab, the FDA-approved HER2 antibody, was found to downregulate HER2 (ErbB2) receptors and enhance TRAIL-mediated apoptotic effects in ovarian and breast cancer cell lines." (PMID 35804815, 2022). "In breast cancers, the most prevalent fusion genes were FGFR family genes (total, 0.48%; FGFR2, 0.34%; FGFR1, 0.14%), ErbB family genes (total, 0.47%; EGFR, 0.20%; ERBB2, 0.27%), ALK (0.27%) and ROS1 (0.07%)." (PMID 36369474, 2022). "HER-2 overexpression or ERBB-2 amplification is universal in many cancers, including breast cancer, colorectal cancer, lung cancer, ovarian cancer, gastric or gastroesophageal junction cancer, and so on." (PMID 36371187, 2022). "One recently published breast cancer cohort also suggested high concordance between tissue IHC/FISH and ERBB2 CNG by ctDNA." (PMID 35126865, 2022). "Of note, NRG1 is a well-known activator of ERBB3/ERBB2 dimers, which are known to play a role in the context of HER2+ breast cancer aggressiveness." (PMID 35664762, 2022).
breast cancer (continued). "This status is rare as we have typically observed, across the breast epithelial and breast cancer samples we have profiled, that EGFR and ERBB2 activity are often jointly active or inactive, consistent with the obligate dimer behavior of ERBB2." (PMID 35879309, 2022). "PAM50 gene analysis showed that in HR+ breast cancer, HER2-low breast cancer had more expressed ERBB2 and luminal-related genes than HER2-zero breast cancer, but not in TNBC." (PMID 36060981, 2022). "EW decreased ErbB2/neu expression and impaired pERK1/ERK2 and AKT phosphorylation in breast cancer cells." (PMID 35209015, 2022). "In clinical therapeutics, Trastuzumab, a humanized monoclonal antibody targeting cells overexpressed ErbB2 (HER2), is administered mainly in HER2-positive breast cancer, offering survival advantage in these patients." (PMID 36359405, 2022). "To neutralize ERBB2 we employed two anti-ERBB2 humanized monoclonal antibodies, namely trastuzumab and pertuzumab, currently used in clinics to treat HER2+ breast cancer patients." (PMID 35664762, 2022). "We previously identified mRNA-based methods involving PCR blood tests for five markers (EPCAM, KRT19, ERBB2, MKI67, and TERT) as an alternative breast cancer screening tool." (PMID 36012405, 2022). "According to histological expression of three receptor proteins, estrogen receptor (ERα; ESR1), progesterone receptor (PGR), and human epidermal growth factor receptor 2 (ERBB2; HER2; Neu), BC is divided into Luminal A, Luminal B, HER-2 positive, and triple-negative breast cancer (TNBC)." (PMID 36345017, 2022). "MCF-7, T-47D and ZR-75-1 are luminal breast cancer lines, SKBR-3 and MDA-MB-453 are ER− but express FOXA1 and AR and are representative of the mApo subtype, with ERBB2-amplification and high expression in SKBR-3 and MDA-MB-453, respectively." (PMID 36358871, 2022). "Our previous study reported higher mRNA levels of the human epidermal growth factor receptor 2 (HER2)-amplicon genes ERBB2 and GRB7 in estrogen receptor (ER)-positive breast cancer patients with relatively high Indigenous American (IA) ancestry from Colombia." (PMID 36620598, 2022). "Overall 60% of patients with ERBB2 CNG by NGS testing had corresponding complete IHC/FISH, including 99% of patients with breast cancer, 40% of patients with GEA, and 35% of patients with other cancers." (PMID 35126865, 2022). "With recent data demonstrating intracranial efficacy of small molecule tyrosine-kinase inhibitors (particularly tucatinib) in ERBB2-positive MBC,28,32 the survival of patients with ERBB2-positive breast cancer BRM is likely to improve even further over time." (PMID 35960523, 2022). "For instance, exosome-mediated transfer of AFAP1-AS1 induced trastuzumab resistance in breast cancer via the interaction with AUF1 and the activation of ERBB2 translation." (PMID 33821219, 2021). "Neu-T mice overexpress rat ErbB2/HER2 in breast tissues and spontaneously develop breast cancer in all mammary glands." (PMID 34579275, 2021). "Recent results demonstrated that pyrotinib, an irreversible pan‐ERBB2 inhibitor, increased DNA damage and enhanced the radiosensitivity of HER2‐overexpressing gastric and breast cancer cells in vitro and in vivo." (PMID 34766149, 2021). "Among these subtypes, breast cancer with amplification and/or overexpression of the human epidermal growth factor receptor 2 (HER2, ErbB2) accounts for about 20% of all human breast cancers." (PMID 34948097, 2021). "The prognosis for female patients with locally advanced breast cancer (LABC) has improved with the emergence of novel drugs, especially for those who have HER2 overexpression or ERBB-2 amplification." (PMID 34722261, 2021).